NEAT1 (nuclear paraspeckle assembly transcript 1)
Diseases named in the same sentence as NEAT1 in open-access papers (continued):
Sharing a sentence is not in itself a finding about the gene and the disease.
hepatocellular carcinoma (97 papers, 2016 to 2026). A malignant tumor that arises from hepatocytes. "More importantly, through rescue experiments, it was found that KIF11 overexpression reversed the senescence phenotype in hepatoma cells caused by NEAT1 deletion." (PMID 37752791, 2023). "We found that NEAT1 deficiency increased the proportion of SA‐β‐Gal positive hepatoma cells and the formation of heterochromatin foci in the nucleus of HepG2 cells." (PMID 37752791, 2023). "Conclusively, NEAT1 overexpression reduces senescence and promotes tumor progression in HCC tissues and hepatoma cells, whereas NEAT1 deficiency causes senescence and inhibits tumor progression in HCC." (PMID 37752791, 2023). "PTBP3 protein can recruit abundant lnc-nuclear enriched abundant transcript 1 (NEAT1) splicing variants to promote hepatocellular carcinoma." (PMID 32670859, 2020). "Studies have shown that NEAT1 is associated with the development of a variety of human diseases, including non-cancerous lesions such as sepsis and neurodegenerative lesions, as well as a variety of cancers such as hepatocellular carcinoma." (PMID 38970092, 2024). "For example, a recent study suggested that high expression of NEAT1 may induce ferroptosis by regulating miR-362-3p in the therapeutic strategy for hepatocellular carcinoma and it is also considered to be a novel diagnostic biomarkers for Alzheimer’s disease." (PMID 39739972, 2024). "Furthermore, NEAT1 deficiency caused senescence in cultured hepatoma cells, and protected against the progression of HCC in a mouse model." (PMID 37752791, 2023). "Interestingly, TTP overexpression in PLC/PRF/5 cells decreased the expression of the long transcript variant of the long-non coding RNA NEAT1, NEAT1_v2, which has been reported to enhance chemoresistance in different cancer cell lines, including hepatoma cells." (PMID 31717307, 2019). "In hepatocellular carcinoma, mTORC1 downregulates the expression of NEAT1/2 and inhibits NEAT1/2-mediated biogenesis of paranuclear spots, thereby promoting mRNA splicing and the expression of critical glycolytic enzymes." (PMID 41584038, 2026). "High BGH3 expression is also observed in HCV-induced hepatocellular carcinoma and correlates with elevated NEAT1 levels." (PMID 41465470, 2025). "Studies have confirmed that transfection of lncRNA NEAT1 small interfering RNA (siRNA) to hepatoma cell HepG2, down-regulation of lncRNA NEAT1 expression, can inhibit the expression of EGFR and Bcl-2, thereby inhibiting tumor cell proliferation and invasion." (PMID 41186893, 2025). "In plenty of human cancers kinds, like hepatocellular carcinoma, melanoma, colon, breast, and pancreatic cancers, NEAT1 serves as an oncogenic lncRNA12." (PMID 40730640, 2025). "LncRNA NEAT1 regulates the progression of hepatocellular carcinoma (HCC) induced by chronic hepatitis C virus by regulating the miR‐9‐BGH3 axis." (PMID 39648148, 2024). "Other studies showed that NEAT1 modulated adipose triglyceride lipase (ATGL) expression, with NEAT1 knockdown reducing human hepatocellular carcinoma cell growth through ATGL." (PMID 39273193, 2024). "We found that knockdown NEAT1 inhibited clone formation and tumour‐spheres formation of hepatoma cells." (PMID 37752791, 2023). "Previous studies revealed that the lncRNAs H19 and NEAT1 were found to directly target miR-193a-3p in Hepatocellular Carcinoma and Lung Adenocarcinoma, respectively." (PMID 36873948, 2023). "SOX9 trans-activated long non-coding RNA NEAT1, which stimulates self-regeneration of hepatocellular carcinoma stem cells via the PKA/Hippo pathway." (PMID 37183261, 2023). "To determine the effect of NEAT1 on senescence in hepatoma cells, we used lentiviral system to stably knockdown or overexpress NEAT1 in HepG2 and Huh7 cells." (PMID 37752791, 2023). "Consistent with the clinical findings, NEAT1 was highly expressed in cultured hepatoma cells compared with normal liver cells." (PMID 37752791, 2023).
hepatocellular carcinoma (continued). "We found that NEAT1 was upregulated in tumor tissues and hepatoma cells, which negatively correlated with a senescence biomarker CDKN2A encoding p16INK4a and p14ARF proteins." (PMID 37752791, 2023). "Altogether, NEAT1 translocated from nucleus to cytoplasm in ROS stress‐induced senescent hepatoma cells." (PMID 37752791, 2023). "First, we measured tumour growth in clone formation and tumour‐spheres formation experiments using control and NEAT1 knockdown hepatoma cells." (PMID 37752791, 2023). "In hepatocellular carcinoma, nuclear enriched abundant transcript 1 (NEAT1), a long noncoding RNA, conferred radioresistance through the induction of autophagy." (PMID 36890567, 2023). "Altogether, these results demonstrate that NEAT1 is decreased in replicative senescence in fibroblasts and ROS stress‐induced senescence in cultured hepatoma cells." (PMID 37752791, 2023). "NEAT1 is upregulated in hepatocellular carcinoma tissues and cell lines compared with normal adjacent tissues and normal cell lines." (PMID 36011001, 2022). "A long noncoding RNA, nuclear paraspeckle assembly transcript 1 (NEAT1) variant 1 (NEAT1v1), confers radioresistance to hepatocellular carcinoma (HCC) cells by inducing autophagy via γ-aminobutyric acid A receptor-associated protein (GABARAP)." (PMID 36430876, 2022). "In contrast, another study showed that a higher level of NEAT1-2 indicates a poor survival rate and can promote proliferation and glycolysis in hepatocellular carcinoma." (PMID 36011001, 2022). "NEAT1 increases the development of hepatocellular carcinoma, NAFLD, and liver fibrosis while acting as a preventative in the pathogenesis of acute-on-chronic liver failure by suppressing the inflammatory response." (PMID 36552725, 2022). "U2AF65-mediated hnRNPA2 elevation also depends on the existence of NEAT1, facilitating the progression of hepatocellular carcinoma." (PMID 36011001, 2022). "Researchers have demonstrated that NEAT1 levels are significantly increased in a variety of tumors, including cholangiocarcinoma, colorectal cancer, and hepatocellular carcinoma." (PMID 34980170, 2022). "This research proved the effects of long non-coding RNA NEAT1 (lncRNA NEAT1) on the viability, proliferation, migration, and invasion of hepatocellular carcinoma cells and explored the mechanism behind these effects." (PMID 36185217, 2022). "NEAT1 was reported to regulate ATGL expression by binding to miR-124-3p during the abnormal lipid metabolism of hepatocellular carcinoma." (PMID 36171622, 2022). "Another study that examined the roles of ncRNAs in hepatocellular carcinoma (HCC) suggested a tumor-promoting role for CD8 T cell-expressed lncRNA NEAT1." (PMID 34830805, 2021). "In the study by Shuai Wang, the NEAT1 paraspeckle promoted the progression of human hepatocellular carcinoma by increasing IL-6/STAT3 signalling." (PMID 33546665, 2021). "For example, it has been revealed that NEAT1 promotes the development of hepatocellular carcinoma cells via regulating the miR-296-5p/CNN2 axis." (PMID 33281971, 2021). "Others have shown that MALAT1 interacts with multiple loci on mtDNA in hepatoma cells, and NEAT1 plays a role in DNA repair processes." (PMID 34943778, 2021). "They found that suppression of NEAT1 in hepatoma cells downregulated the expression of ATGL, and subsequently decreased levels of cellular DAG and FFA, which led to the suppression of HCC cell proliferation." (PMID 35053204, 2021). "ATGL and its products (DAG and FFA) have been shown to be responsible for NEAT1-mediated hepatocellular carcinoma cell growth." (PMID 34416900, 2021). "For instance, NEAT1 suppressed sorafenib sensitivity of hepatocellular carcinoma cells via regulating miR-335/c-Met." (PMID 34222227, 2021).
hepatocellular carcinoma (continued). "Another study found that NEAT1 disrupts the lipolysis of hepatoma cells via a lipolytic enzyme adipose triglyceride lipase (ATGL), which ultimately maintains a high level of free fatty acid and diacylglycerol that favors HCC cell growth." (PMID 33808647, 2021). "In this section, we summarize the roles of the NEAT1/miRNA/target axis in digestive system tumors, including oral squamous cell carcinoma, esophageal squamous cell carcinoma, gastric cancer, hepatocellular carcinoma, and colorectal cancer." (PMID 34512157, 2021). "NEAT1 also sponged miR-335 in hepatocellular carcinoma, acute lymphoblastic leukemia, gastric cancer and pancreatic cancer." (PMID 31868202, 2020). "In hepatocellular carcinoma, inhibition of NEAT1 suppresses tumor growth, migration and invasion in vitro." (PMID 32983133, 2020). "NEAT1 was found to facilitate hepatocellular carcinoma cell proliferation as a result of its interaction with miR-129." (PMID 32692721, 2020). "NEAT1 is crucially interplaying with miRNA also in hepatocellular carcinoma acting as a ceRNA and therefore reducing expression of these miRNA in the case of (a) miR‐129‐5p, (b) miR‐613, (c) miR‐485, and (d) miR‐139‐5p." (PMID 30430751, 2019). "Further analysis of NEAT1 demonstrated that NEAT1 knockdown increases hepatocellular carcinoma cells sensitivity to sorafenib." (PMID 35582574, 2019). "It was reported that long non‐coding RNA nuclear‐enriched abundant transcript 1 (NEAT1) is involved in hepatocellular carcinoma (HCC)." (PMID 30346062, 2019). "The expression of NEAT1 was increased by the treatment with 5-AZA in hepatocellular carcinoma cells, indicating that DNA methylation is an important determinant of NEAT1 expression." (PMID 30374364, 2018). "Further experiments are clearly needed to shed light on the impact of PSF sequestering by NEAT1 on host genes regulation and on the occurrence of fulminous hepatocellular carcinomas following HDV infection." (PMID 29662142, 2018). "NEAT1 had higher expression in the hepatocellular carcinoma (HCC), which promoted the clinical features of HCC." (PMID 26911892, 2016). "However, in other diseases like hepatocellular carcinoma, previous work analyzing autophagy-related pathways suggested a role for NEAT1 in the triglyceride (TG) metabolism by being an upregulator of miR-372-3p in both RAPA-treated mice and in a cell model." (PMID 38212456, 2024). "Moreover, NEAT1 knockdown sensitized liver cancer cells to sorafenib and lenvatinib, both clinically used for treating hepatocellular carcinoma, whereas it conferred resistance to an AKT-targeted drug, capivasertib." (PMID 36826016, 2023). "As same in gastric cancer, ALKBH5 also could up-regulate LncRNA NEAT1 expression by inhibiting m6A enrichment on LncRNA NEAT1 in hepatocellular carcinoma and in colon cancer." (PMID 37365581, 2023). "This indicates that knockdown NEAT1 reduces self‐renewal ability of cultured hepatoma cells." (PMID 37752791, 2023). "NEAT1 was reduced in senescent hepatoma cells induced by doxorubicin (DOXO) or serum starvation." (PMID 37752791, 2023). "This indicates that the effect of NEAT1 on hepatoma cell senescence is dependent on KIF11." (PMID 37752791, 2023). "As ROS stress induced senescence of hepatoma cells and increased NEAT1 expression in the cytoplasm." (PMID 37752791, 2023). "It has been found that the lncRNA NEAT1 disrupted hepatocellular carcinoma lipolysis by regulating adipose triglyceride lipase, thereby driving hepatocellular carcinoma proliferation.In conclusion, LncRNAs are involved in the regulation of various lipid metabolism-related genes in cancer cells." (PMID 36387240, 2022). "NEAT1-mediated abnormal lipolysis promotes the growth of hepatocellular carcinoma cells." (PMID 36362406, 2022).
hepatocellular carcinoma (continued). "In a study that investigating the mechanism of NEAT1 in hepatocellular carcinoma tissues, NEAT1 could regulate the expression of epidermal growth factor receptor (EGFR), thereby contributing to cancer cell proliferation." (PMID 34630395, 2021). "Studies have shown that lncRNA CNC-TIM3 exacerbates CD8 T cell failure by binding to TIM-3 in hepatocellular carcinoma, and down-regulating lncRNA NEAT1 can inhibit apoptosis of CD8+ T cells and increase the anti-tumor activity of CD8+ T cells in hepatocellular carcinoma." (PMID 33585256, 2020). "The lncRNA NEAT1 also interacts with KAT2A to promote deterioration of hepatocellular carcinoma." (PMID 31320749, 2020). "Thus, we demonstrated that NEAT1 promotes the malignant biological properties of hepatocellular carcinoma by negatively regulating miR‐384." (PMID 30346062, 2019). "Our results demonstrated that NEAT1 disrupts the lipolysis of hepatoma cells via ATGL." (PMID 29764424, 2018). "NEAT1 could facilitate the initiation of hepatocellular carcinoma and predict poor prognosis outcome." (PMID 30053878, 2018). "Next, we investigated the effect of NEAT1 on lipolysis in hepatoma cells." (PMID 29764424, 2018). "Additionally, in HepG2 cells, a hepatocellular carcinoma cell line, higher substrate stiffness amplifies nuclear paraspeckle assembly transcript 1 (NEAT1) expression, which activates the EMT process and cell proliferation by activating the WNT/β-catenin signaling pathway." (PMID 38544822, 2024). "Therefore, NEAT1 represses senescence in cultured hepatoma cells." (PMID 37752791, 2023). "The regulatory role of NEAT1 on T cells functions has been validated in different contexts, including sepsis, primary Sjögren’s syndrome, RA and hepatocellular carcinoma (HCC)." (PMID 34804042, 2021). "Another group also found that the expression of NEAT1 was significantly increased in hepatocellular carcinoma (HCC) tissues and NEAT1 promotes tumor cell EMT, migration, and invasion capacities." (PMID 32596382, 2020). "In hepatocellular carcinoma (HCC), lncRNA Nuclear Enriched Abundant Transcript 1 (NEAT1) functioned as competing endogenous lncRNA (ceRNA) to regulate STAT3 by sponging miR-485 for HCC development." (PMID 29654165, 2018). "There is evidence that a long non-coding RNA (lncRNA), nuclear-enriched abundant transcript 1 (NEAT1) variant 1 (NEAT1v1), could promote autophagy through GABARAP and lead to radio-resistance of hepatocellular carcinoma (HCC) cells." (PMID 40900801, 2025). "In hepatocellular carcinoma (HCC), the long non-coding RNA NEAT1 has been reported to indirectly upregulate MIOX expression by modulating miR-362-3p, thereby promoting ferroptosis in HCC cells." (PMID 41020866, 2025). "Overexpression of NEAT1 and AKT2 promotes proliferation and invasion of hepatocellular carcinoma cells, inhibits apoptosis, and increases the invasive capacity of malignant cells." (PMID 41465470, 2025). "For instance, NEAT1 upregulates ATG3 to enhance autophagy, thereby increasing resistance to sorafenib in hepatocellular carcinoma cells." (PMID 39715205, 2024). "Further studies described a modulating role of NEAT1 with regard to the expression of adipose triglyceride lipase (ATGL) expression, and knockdown of NEAT1 attenuated human hepatocellular carcinoma cell growth through ATGL." (PMID 38212456, 2024). "High expression of NEAT1 or KIF11 inhibits hepatocellular senescence in clinical HCC and cultured hepatoma cells." (PMID 37752791, 2023). "Based on our discovery, NEAT1 and KIF11 are overexpressed in HCC tissues and hepatoma cells, and both are negatively correlate with senescence." (PMID 37752791, 2023). "We then detected the expression of NEAT1, p16 and p14 in cultured normal liver cells (i.e., HLSEC and THLE‐3) and different hepatoma cell lines (i.e., HCCLM3, Huh7, HepG2 and SNU398)." (PMID 37752791, 2023).
hepatocellular carcinoma (continued). "Then, we determined the expression of NEAT1, p16 and p14 in starvation or DOXO‐treated normal liver epithelial cells (THLE‐3) and hepatoma cells (HepG2 and Huh7)." (PMID 37752791, 2023). "Downregulation of NEAT1 inhibits EGFR expression, promotes hepatoma cell apoptosis, and inhibits the cell cycle, thereby inhibiting tumor proliferation and invasion." (PMID 36980210, 2023). "Knockdown NEAT1 or KIF11, serum starvation, H2O2 or DOXO treatment are the ways to induce senescence in hepatoma cells." (PMID 37752791, 2023). "In hypoxic hepatocellular carcinoma (HCC), NEAT1 sponges miR-199a-3p to promote cell proliferation by increasing the expression of UCK2." (PMID 35625948, 2022). "In hepatocellular carcinoma cells, treatment with 5-AZA enhanced NEAT1 expression, demonstrating that DNA methylation is a significant determinant of NEAT1 expression." (PMID 35581633, 2022). "NEAT1 can also sponge miR-124-3p, elevating the expression of ATGL1, which promotes the lipolysis and cancer progression in hepatocellular carcinoma." (PMID 36011001, 2022). "NEAT1 promotes autophagy and fortifies cell resistance to sorafenib through sponging miR-204 and modulating ATG3 in hepatocellular carcinoma." (PMID 31868202, 2020). "In hepatocellular carcinoma, BCLAF1 promotes cell proliferation, invasion and 5-Fluorouracil resistance though targeting NEAT1." (PMID 33298086, 2020). "On the other hand, in three renal carcinomas (chromophobe (KICH), clear cell carcinoma (KIRC), and papillary cell carcinoma (KIRP)), hepatocellular carcinoma (LIHC), and prostate adenocarcinoma (PRAD), NEAT1 expression was significantly increased." (PMID 31186635, 2019). "Recent studies elucidating the role of NEAT1 in hepatocellular carcinoma could show an upregulation of this lncRNA in HCC patient tissue and HCC cell lines." (PMID 30430751, 2019). "Similarly, NEAT1 expression negatively correlated with p16 and p14 levels in starvation or DOXO‐treated normal liver cells and hepatoma cells." (PMID 37752791, 2023). "During senescence, NEAT1 translocated into cytosol and interacted with a motor protein KIF11, resulting in KIF11 protein degradation and subsequent increased expression of CDKN2A in cultured hepatoma cells." (PMID 37752791, 2023). "NEAT1 can elevate the expression of many factors, including SMO, LAGE3, AKT2, TGF-β1, and STAT3, which can increase the proliferation and metastasis both in vivo and in vitro, accelerating the progression of hepatocellular carcinoma." (PMID 36011001, 2022). "Moreover, by sequestering hsa-miR-335-5p, NEAT1 induces AKT phosphorylation and c-MET expression in hepatocellular carcinoma cells." (PMID 35008626, 2021). "Additionally, NEAT1 negatively correlated with p16/p14 levels in both normal liver cells and hepatoma cells without treatments." (PMID 37752791, 2023). "In hepatocellular carcinoma (HCC) and non-small-cell lung cancer (NSCL), the EMT process was promoted by the overexpression of the long-non-coding RNA NEAT1 induced by HIF-2α." (PMID 35745656, 2022). "Similarly, a recent study reported the binding of miR-let-7b to NEAT1 as well as a negative correlation of NEAT1 expression with miR-let-7b expression in hepatocellular carcinoma tissues." (PMID 34416900, 2021). "LncRNA nuclear-enriched abundant transcript 1 (NEAT1) activates autophagy via regulating ATG3 or Beclin1 expression and inhibits chemotherapeutic efficacy in hepatocellular carcinoma (HCC) and colorectal cancer." (PMID 33239065, 2020). "A previous report has shown that only NEAT1_2, but not NEAT1, is significantly correlated with poor overall survival of hepatocellular carcinoma (HCC) patients and promotes tumor development by mediating paraspeckle biogenesis." (PMID 38898019, 2024).